LINC01571 (long independently transcribed non-coding RNA 1571)
Synonyms: TCONS_00024399
Gene: Long non-coding RNA gene on chromosome 16 (51,754,628 to 51,795,169, forward strand). Ensembl gene ENSG00000260057.
Diseases named in the same sentence as LINC01571 in open-access papers:
LINC01571 is named in the same sentence as 1 disease in open-access papers, as found by Europe PMC text mining. Sharing a sentence is not in itself a finding about the gene and the disease. The quoted sentences say what the papers report.
glioma (1 paper, 2023). A benign or malignant brain and spinal cord tumor that arises from glial cells (astrocytes, oligodendrocytes, ependymal cells). "HCG15, AC007950.2, PTPRN2-AS1, LEF1-AS1, AC021739.2, ARHGAP42-AS1, and LINC01571 were found to be highly expressed in glioma tissues, while TRHDE-AS1 and AC008915.2 were highly expressed in normal cells." (PMID 37101543, 2023). "HCG15, AC007950.2, PTPRN2-AS1, LEF1-AS1, AC021739.2, ARHGAP42-AS1, and LINC01571 were highly expressed in glioma tissues." (PMID 37101543, 2023).